KLF7 (KLF transcription factor 7)
Diseases named in the same sentence as KLF7 in open-access papers (continued):
Sharing a sentence is not in itself a finding about the gene and the disease.
cardiac hypertrophy (3 papers, 2023 to 2024). "KLF7 regulates enzymes in glycolysis and fatty acid oxidation to attenuate metabolic imbalances caused by cardiac hypertrophy." (PMID 38516000, 2024). "Furthermore, cardiac-specific knockdown phosphofructokinase-1, liver or overexpression long-chain acyl-CoA dehydrogenase partially rescues the cardiac hypertrophy in adult male KLF7 deficient mice." (PMID 36810848, 2023). "A recent study highlighted the role of the KLF7/PFKL/ACADL axis in regulating myocardial metabolic remodeling during myocardial hypertrophy." (PMID 38347951, 2024). "Although we focused on PFKL and ACADL in the present study, it is very likely that the expression of other genes is also controlled by transcriptional programs involving KLF7 to induce cardiac hypertrophy." (PMID 36810848, 2023). "Analysis of the top DEGs revealed that KLF7 knockout resulted in significant variations in the expression of genes related to cardiac hypertrophy, glucose and lipid metabolism, cardiac contractile function and the extracellular matrix." (PMID 36810848, 2023). "We have shown that knockout or overexpression Klf7 can induce cardiac hypertrophy and HF by disturbing the cardiac metabolic balance and serve as a metabolic molecular switch to repress and activate genes involved in cardiac glycolysis and FAO." (PMID 36810848, 2023). "Here, the authors show that KLF7 can simultaneously regulate key enzymes in glycolysis and fatty acid oxidation to mitigate metabolic imbalance during cardiac hypertrophy." (PMID 36810848, 2023). "In this study, we reveal the critical transcriptional role of KLF7 in pathological cardiac hypertrophy and cardiac metabolism." (PMID 36810848, 2023). "In addition, we sought to determine the functional involvement of KLF7 in stress-induced cardiac hypertrophy in vivo." (PMID 36810848, 2023). "Thus, to assess whether KLF7 can trigger pathological cardiac hypertrophy by balancing the expression of PFKL and ACADL in vivo, we generated transgenic mice (TG) in a cardiac myocyte-specific manner." (PMID 36810848, 2023). "Then, we sought to determine whether the KLF7/PFKL/ACADL axis regulates cardiac hypertrophy growth." (PMID 36810848, 2023). "Collectively, these findings suggest that cardiac-specific knockout KLF7 disturbed the expression of key enzymes in the glycolysis and FAO and impaired the metabolic balance of the heart, thereby inducing concentric cardiac hypertrophy." (PMID 36810848, 2023). "KLF7 can simultaneously activate and repress the expression of ACADL and PFKL respectively to mediate the pathological progression of cardiac hypertrophy." (PMID 36810848, 2023). "Our findings show that KLF7/PFKL/ACADL signaling has been shown to be an essential process for cardiac FAO and glycolysis, leading to cardiac hypertrophy and HF." (PMID 36810848, 2023). "To clarify whether KLF7 is involved in the process of cardiac hypertrophy, we used AngII to treat human cardiomyocyte cell line AC16 to induce cardiomyocyte hypertrophy model, and the results showed that the expression of Klf7 decreased in hypertrophic cardiomyocytes." (PMID 36810848, 2023).
colon adenocarcinoma (3 papers, 2023 to 2024). "Further research is needed to elucidate the underlying mechanisms by which KLF7 contributes to tumor progression and metastasis and to explore its therapeutic implications in colon adenocarcinoma." (PMID 38116138, 2023). "The correlation analysis conducted in our study reveals significant associations between high KLF7 expression and advanced tumor stage, lymph node metastasis, and poor tumor differentiation in colon adenocarcinoma." (PMID 38116138, 2023). "High expression of KLF7 was associated with poorer survival outcomes in colon adenocarcinoma patients, and multivariate Cox regression analysis identified KLF7 expression as an independent prognostic factor for cancer-specific survival." (PMID 38116138, 2023). "Future studies should focus on elucidating the molecular mechanisms underlying the tumorigenic effects of KLF7 in colon adenocarcinoma and investigating the efficacy of targeting KLF7 for therapeutic intervention." (PMID 38116138, 2023). "The identification of KLF7 as a tumor-promoting factor in colon adenocarcinoma has important implications for both diagnosis and therapy." (PMID 38116138, 2023). "Our study provides further evidence for the upregulation of KLF7 expression in colon adenocarcinoma tissues, consistent with its involvement in tumor progression and metastasis." (PMID 38116138, 2023). "Gaining insight into the contribution of KLF7 to colon adenocarcinoma pathogenesis can provide valuable understanding of disease mechanisms and identify novel prognostic biomarkers and therapeutic targets." (PMID 38116138, 2023). "Here, we aimed to determine the expression and functional significance of KLF7 in colon adenocarcinoma." (PMID 38116138, 2023). "The clinical data from our medical center and the TCGA dataset further support the significance of KLF7 expression in colon adenocarcinoma." (PMID 38116138, 2023). "Overall, our study adds to the existing body of knowledge regarding the role of KLF7 in cancer, particularly in colon adenocarcinoma." (PMID 38116138, 2023). "In this study, our objective was to explore the expression and functional significance of KLF7 in colon adenocarcinoma." (PMID 38116138, 2023). "The Krüppel-like factor 7 (KLF7), a transcription factor, has been associated with various malignancies, yet its specific role in colon adenocarcinoma remains largely unexplored." (PMID 38116138, 2023). "The relationship between KLF7 expression and immune cell infiltration in colon adenocarcinoma was also investigated." (PMID 38116138, 2023). "This consistency across different cancer types supports the potential of KLF7 as a biomarker for assessing tumor aggressiveness and prognosis in colon adenocarcinoma." (PMID 38116138, 2023). "The prognostic significance of KLF7 expression in colon adenocarcinoma (COAD) was assessed using cancer-specific survival (CSS) analyses." (PMID 38116138, 2023). "Our findings revealed a significant upregulation of KLF7 expression in colon adenocarcinoma tissues compared to adjacent normal tissues." (PMID 38116138, 2023). "While our study provides valuable insights into the role of KLF7 in colon adenocarcinoma, it is essential to acknowledge its limitations." (PMID 38116138, 2023). "The functional role of KLF7 in colon adenocarcinoma was investigated both in vitro and in vivo." (PMID 38116138, 2023). "Consequently, comprehending the expression patterns and functional implications of KLF7 in colon adenocarcinoma is vital for understanding its precise role and potential therapeutic implications." (PMID 38116138, 2023). "Moreover, elevated KLF7 expression correlated with advanced tumor stage, lymph node metastasis, and poor overall survival in colon adenocarcinoma patients." (PMID 38116138, 2023). "Indeed, functional assays conducted in our study provided mechanistic insights into the tumor-promoting role of KLF7 in colon adenocarcinoma." (PMID 38116138, 2023).
colon adenocarcinoma (continued). "The mRNA level of KLF7 in colon adenocarcinoma tissues was assessed using RT-qPCR." (PMID 38116138, 2023). "Incorporating KLF7 expression into existing prognostic models may improve their accuracy and enable personalized treatment strategies for colon adenocarcinoma patients." (PMID 38116138, 2023). "However, the specific role of KLF7 in colon adenocarcinoma remains largely unexplored." (PMID 38116138, 2023). "Silencing KLF7 led to a significant reduction in cell proliferation, as demonstrated by the CCK-8 assay conducted on colon adenocarcinoma cells." (PMID 38116138, 2023). "A thorough analysis was performed to assess the expression patterns of KLF7 in colon adenocarcinoma (COAD) compared to nontumorous colon tissues." (PMID 38116138, 2023).
colon cancer (3 papers, 2011 to 2023). "KLF7 (N K27 to T K4), a transcription factor belonging to the KLF family that plays critical roles in differentiation, development, and maintenance of tissue homeostasis, but, to the best of our knowledge, without a specific role in colon cancer." (PMID 22011431, 2011).
peripheral nerve injury (3 papers, 2017 to 2024). Injury to a peripheral nerve. "In peripheral nerve injury, KLF7 upregulation strategies have supported that KLF7 promotes axonal regeneration in injured nerves and that it acts as a growth-promoting transcription factor in injured neurons." (PMID 28884027, 2017). "Combined with the results of RNA-Seq and RT-PCR, we found that the regulation of Klf7 gene expression may be a potential therapeutic strategy for peripheral nerve injury." (PMID 32587647, 2020). "In instances of CNS and peripheral nerve injury (PNI), the upregulation of KLF7 has been shown to promote growth, axonal regeneration, and sprouting in damaged nerves." (PMID 39700118, 2024).
prostate carcinoma (3 papers, 2023 to 2025). A carcinoma that arises from epithelial cells of the prostate gland. "Our results indicated that FFA C8:0 further regulates IL-6/p21 expression by regulating KLF7 and participates in the occurrence and development of prostate cancer." (PMID 37170248, 2023). "PA-activated GPRs/KLF7/CCL2 pathway in BMA facilitates prostate cancer growth and metastasis." (PMID 38221626, 2024). "Furthermore, PCa cells were treated with FFA C8:0 and interfered with KLF7 expression, results showed that FFA C8:0 could promote the occurrence of prostate cancer by regulating KLF7." (PMID 37170248, 2023).
autism spectrum disorder (2 papers, 2022 to 2025). A spectrum of developmental disorders that includes autism, and Asperger syndrome. "Studies have shown that Klf7-deficient mice similarly exhibit traits associated with neurological conditions such as autism spectrum disorder and intellectual disability." (PMID 40762575, 2025). "Klf7 has been recently identified as a causal gene for autism spectrum disorder, but leaving a lot to be discovered." (PMID 36207723, 2022). "Krüppel-like factor 7 (klf7), a transcription factor in the nervous system to regulate cell proliferation and differentiation, has been recently identified as a causal gene for autism spectrum disorder (ASD), but the mechanism behind remains unknown." (PMID 36207723, 2022). "Krüppel-like factor 7 (KLF7), a member of the Krüppel-like transcription factor family, is a candidate gene for autism spectrum disorder (ASD), associated with deletions at 2q33.3-q34." (PMID 40762575, 2025). "Krüppel-like factor 7 (KLF7), a transcription factor associated with autism spectrum disorder and intellectual developmental disorders, plays a pivotal role in brain development." (PMID 40762575, 2025). "Klf7 has been proposed as a candidate gene for autism spectrum disorder (ASD) with the results that patients with deletion in 2q33.3q34, where klf7 is located, show autistic traits." (PMID 36207723, 2022).
bladder cancer (2 papers, 2022 to 2023). "Our analysis revealed a network of TFs whose activity could be essential to Basal bladder cancer biology, including HMGA2, KLF7, NR3C1 and ZBED2." (PMID 36944729, 2023).
coronary artery disease (2 papers, 2023). "Moreover, KLF7 has been identified as one of the core transcription factors that regulate coronary artery disease-associated pathways." (PMID 36698180, 2023).
glucose metabolic disorders (2 papers, 2022 to 2024). "This study is intend to explore whether PA promoting KLF7 expression through GPRs/NF-κB signaling pathway, causing inflammation and glucose metabolism disorders." (PMID 35443706, 2022). "Therefore, our results and previous studies demonstrated that PA could induce inflammatory response and glucose metabolic disorders by promoting KLF7, while the specific molecular mechanism needs to be further explored." (PMID 35443706, 2022).
head and neck squamous cell carcinoma (2 papers, 2024 to 2025). A squamous cell carcinoma that arises from any of the following anatomic sites: lip and oral cavity, nasal cavity, paranasal sinuses, pharynx, larynx, and salivary glands. "For instance, KLF7 binds to the IGF2BP2-SE to drive IGF2BP2 overexpression and promote tumor progression in head and neck squamous cell carcinoma (HNSCC), while TP63 and SOX2 co-activate SEs and the promoter of CCAT1 to drive tumorigenesis in squamous cell carcinomas (SCCs)." (PMID 41462308, 2025).
leukemia (2 papers, 2014 to 2021). A malignant (clonal) hematologic disorder, involving hematopoietic stem cells and characterized by the presence of primitive or atypical myeloid or lymphoid cells in the bone marrow and the blood. "To investigate the significance of Class I HDACs (HDAC1, HDAC2, HDAC3, and HDAC8), HDAC11, and Klfs (Klf1, KLf3, Klf4, and Klf7) in the pathogenesis of human leukemia, we used real-time RT-PCR to evaluate the expression of HDACs and Klfs in bone marrow samples from human leukemia patients." (PMID 25341045, 2014).
lung adenocarcinoma (2 papers, 2021 to 2025). A carcinoma that arises from the lung and is characterized by the presence of malignant glandular epithelial cells. "At the transcriptional level, BACH1 can promote lung adenocarcinoma cell metastasis by directly activating ITGA2 transcription, and KLF7 has been shown to regulate ITGA2 expression to maintain oral cancer stem cell properties." (PMID 40940943, 2025).
Anxiety (1 paper, 2025). Intense feelings of nervousness, tension, or panic often arise in response to interpersonal stresses. "KLF7 mutant mice exhibited abnormal neuronal projections, anxiety- and depression-like behaviors, and memory impairments." (PMID 40762575, 2025). "Given the essential role of hippocampal connectivity in spatial navigation, memory consolidation, and anxiety- and depression-related behaviors, a series of behavioral tests was conducted to investigate the effects of KLF7 deletion." (PMID 40762575, 2025). "Our behavioral analyses revealed that Emx1-Cre; Klf7F/F mutant mice exhibit depressive- and anxiety-like behaviors, as well as memory impairments, underscoring the role of Klf7 in hippocampal function." (PMID 40762575, 2025). "Furthermore, KLF7 mutant mice exhibited abnormal neuronal projections, as well as anxiety- and depression-like behaviors, and impairments in memory function." (PMID 40762575, 2025).
atherosclerosis (1 paper, 2025). A disease characterized by the build-up of fatty material and calcium deposition in the arterial wall resulting in partial or complete occlusion of the arterial lumen. "Overexpression of KLF7 alleviates atherosclerosis lesions and restores metabolic abnormalities in atherosclerosis mice, while inhibiting glucose intake and glucose metabolic reprogramming in ox-LDL-induced RAW264.7 cells." (PMID 41373858, 2025).
Atrophy (1 paper, 2025). Any weakening or degeneration, especially through lack of use. "Here, we further demonstrate that targeted deletion of KLF7 in neural progenitor cells leads to severe hippocampal atrophy and a significant reduction in neuronal numbers in the CA and DG regions, underscoring its pivotal role in forebrain development and hippocampal formation." (PMID 40762575, 2025).
brain injury (1 paper, 2025). Acute and chronic (see also brain INJURIES, CHRONIC) injuries to the brain, including the cerebral hemispheres, CEREBELLUM, and brain STEM. "Our findings reveal an important role of the KLF7/MKNK2/HIF‐1 axis in IS, and targeting this axis may be a promising strategy to alleviate IS‐induced brain injury." (PMID 40923147, 2025).
branchio-oto-renal syndrome (1 paper, 2021). "KLF7 has been considered as one high quality candidate gene for human branchio-oto-renal syndrome, which is an autosomal dominant disease with hearing loss as one clinical sign." (PMID 33805165, 2021).
breast tumor (1 paper, 2022). "Moreover, KLF7 correlated with nucleolar characteristics in human breast tumor tissue, indicating a role for KLF7 in ribosomal biogenesis." (PMID 36192788, 2022).
cerebral infarction (1 paper, 2025). An ischemic condition of the brain, producing a persistent focal neurological deficit in the area of distribution of the cerebral arteries. "In contrast, reactivation of MKNK2 not only offset the alleviation of the cerebral infarction by KLF7 overexpression but also exacerbated this pathology." (PMID 40923147, 2025). "In addition, TTC showed that overexpression of KLF7 reduced the volume of cerebral infarction in rats compared with the oe‐NC group." (PMID 40923147, 2025).
colorectal adenocarcinoma (1 paper, 2023). The most common type of colorectal carcinoma. "Likewise, analysis of public RNA sequencing data revealed upregulation of KLF7 mRNA in colorectal adenocarcinomas at the primary tumor site." (PMID 36890812, 2023).
colorectal tumor (1 paper, 2023). "Bioinformatic analyses showed that both KLF7 and ADAM19 are upregulated in colorectal tumors as well as associated with worse survival and their downregulation impaired HCT116 clonogenic activity." (PMID 36890812, 2023). "Antagonizing this axis may potentially suppress colorectal tumor formation, and likewise the inhibition of BHLHE40-regulated genes such as ADAM19 or KLF7 may have therapeutic value." (PMID 36890812, 2023).
complex partial seizures (1 paper, 2022). "Patients with loss of klf7 show complex partial seizures, which is consistent with the epilepsy-related characteristics of klf7+/− mice." (PMID 35328799, 2022).
deafness (1 paper, 2021). An inherited or acquired condition characterized by the complete loss of the ability to hear from one or both ears. "There is good evidence here that the KLF7 variant contributes to deafness, but the genotyping data supports the view that this is a multigene/multifactorial disease, and so this is one contributing mutation." (PMID 33805165, 2021). "We identified a unique missense variant in Kruppel-like factor 7 (KLF7) gene significantly associated with deafness in ASCDs." (PMID 33805165, 2021). "Furthermore, the penetrance of deafness in ASCD calculated based on the KLF7 variant was 0.75, which was in agreement with the previously calculated penetrance of 0.72." (PMID 33805165, 2021). "The incomplete penetrance presented by the KLF7 variant in deafness may be related to its role as a transcription factor that is involved in a specific part of the hearing pathway." (PMID 33805165, 2021). "In conclusion, KLF7 is a promising candidate gene causative for ASCD deafness." (PMID 33805165, 2021). "Functional analysis of KLF7 regarding ear development may provide further evidence for its role in deafness." (PMID 33805165, 2021). "As KLF7 plays an important role in the nervous system, is expressed in the inner ear, and seems to be involved in inner ear development, it was a convincing candidate for ASCD deafness." (PMID 33805165, 2021).
developmental delay (1 paper, 2022). "In addition, another study reported four unrelated individuals with de novo mutations in klf7 accompanied by ASD-related developmental delay/intellectual disability (DD/ID) and neuromuscular and psychiatric complications." (PMID 35328799, 2022).
dilated cardiomyopathy (1 paper, 2024). Cardiomyopathy which is characterized by dilation and contractile dysfunction of the left and right ventricles. "Endothelial cell analysis further revealed COL25A1, NFIB, and KLF7 as significant genes for dilated cardiomyopathy, hypertrophic cardiomyopathy, and Tetralogy of Fallot." (PMID 39202774, 2024).
gall bladder cancer (1 paper, 2025). "MiR-4733, on the contrary, seems to have tumor-promoting properties in gall bladder cancer cells, as it directly suppressed expression of KLF7, an anti-oncogene, and E-cadherin, a key player in the epithelial-mesenchymal transition process." (PMID 40282319, 2025).